NLRP3 (NLR family pyrin domain containing 3)
Diseases named in the same sentence as NLRP3 in open-access papers (continued):
Sharing a sentence is not in itself a finding about the gene and the disease.
inflammation (continued). "Data from Crataegus aronia extracts showed inhibition of the nuclear accumulation of NF-κB and NLRP-3 protein levels and caspase-1 in HFD-induced aortic vascular inflammation in rats, thus suggesting inhibition of the NLRP3 inflammasome-mediated pathway." (PMID 32153414, 2020). "High-fat diet–induced renal inflammation involves the P2X7 receptor via the activation of NLRP3 inflammasome, whereas reduced kidney damage, inflammation, and decreased NLRP3 upregulation are observed in mice genetically depleted of the receptor." (PMID 32528404, 2020). "Activation of inflammasome-dependent NLRP3 is important for renal RMNCs and parenchymal cells in relation to sterile and chronic inflammation in various kidney diseases." (PMID 31694192, 2019). "Despite the weak evidence for an interaction of the NLRP3 inflammasome and IL-33 pathway in sterile liver inflammation, a NLRP3-IL-33 axis has been shown in other diseases." (PMID 30213101, 2018). "One well studied inflammasome is the NLRP3 inflammasome, which contributes to the development of sterile liver inflammation in ALD and NAFLD." (PMID 30213101, 2018). "Nlrp3 contributes to renal inflammation through its classical function of caspase-1-mediated cleavage and subsequent release of effector cytokines." (PMID 24454932, 2014). "Whereas ovalbumin-induced airway inflammation requires NLRP3 and IL-1β, house dust mite allergens induce pathology in an NLRP3-independent fashion." (PMID 24312100, 2013). "Uric acid released from injured tissue is considered a major endogenous danger signal and local instillation of uric acid crystals induces acute lung inflammation via activation of the NLRP3 inflammasome." (PMID 23226314, 2012). "Escherichia-Shigella has been associated with NOD-like receptor protein 3 (NLRP3) inflammasome activation and elevated TNF-α production, contributing to renal inflammation, whereas Faecalibacterium and Bifidobacterium exert SCFA-mediated anti-inflammatory effects." (PMID 40978750, 2025). "In addition, our cell experiments showed that EBN attenuated cigarette smoke-induced pulmonary inflammation mainly by inhibiting the tumor necrosis factor receptor 1 (TNFR1)/nuclear factor-kappa B (NF-κB)/NLRP3 pathway." (PMID 38873472, 2024). "The TLR4/NLRP3 pathway is critical in the pathogenesis of ALI, causing sustained production of cellular factors such as IL‐1β and IL‐18, which ultimately leads to a massive outbreak of lung inflammation, resulting in tissue injury and even ARDS." (PMID 39139945, 2024). "Similarly, pulmonary inflammation and fibrosis are efficiently ameliorated by inhibiting the NLRP3-PYCARD interaction and pyroptosis." (PMID 38343546, 2024). "In this study, NLRP3 inflammasome activation in AMs may have contributed to lung inflammation induced by O3." (PMID 39420831, 2024). "The activation of NLRP3 inflammasome and MyD88 myddosome increases the secretion of pro-inflammatory cytokines, such as IL-β, thereby contributing to chemotherapy-induced cardiac inflammation and fibrosis." (PMID 38700665, 2024). "For instance, a large number of NE1 cells were expressed with mature neutrophil markers (e.g., Retnlg, Lcn2, and Asprv1, associated with chronic inflammation), while NE2 cells were highly expressed with pro-inflammatory molecules (e.g., Tnf, Il1b, and Nlrp3, which trigger acute inflammation)." (PMID 37781362, 2023). "PM2.5 has induced pulmonary inflammation via the NLRP3 pathway." (PMID 37215119, 2023). "Although the NLRP3 inflammasome is a key player in antiviral responses, it also leads to an excessive innate immune response, which is implicated in RSV-induced lung inflammation and damage." (PMID 37798799, 2023). "GO-203 exacerbated TLR4/MyD88/NF-κB pathway activation in vivo, and NLRP3 inflammasome-mediated pyroptosis reduced in a mouse model of asthmatic neutrophil airway inflammation induced by OVA/LPS; these pathological changes were partially alleviated after TAK-242 application." (PMID 37880668, 2023).
inflammation (continued). "The DEK/ATAD3A/DRP1 signaling axis may mediate the effects of DEK on mitophagy and NLRP3 inflammasome in asthmatic airway inflammation." (PMID 38274803, 2023). "In addition, we highlight the pivotal role that the NLRP3 inflammasome plays in inflammation-related diseases." (PMID 37370025, 2023). "Some studies showed that the NLRP3 inflammasome resulted in liver inflammation and fibrosis." (PMID 36983568, 2023). "Since our data show the role of NLRP3 in pulmonary inflammation induced by both acute and subchronic CS-exposure in mice, we next used the acute exposure model as previously in order to investigate the mechanism of NLRP3-mediated lung inflammation." (PMID 36045672, 2022). "Furthermore, circulating TMAO induces low-grade chronic systemic inflammation and increases levels of inflammatory cytokines by promoting NF-κB activation and activating the NLRP3 inflammasome." (PMID 35975941, 2022). "NLRP3 inhibitor MCC950 has been shown to prevent LPS-induced pulmonary inflammation in mice." (PMID 36248872, 2022). "NLRP3 inflammasome-dependent IL-1β production also acts as a major chemoattractant of neutrophils and contributes to the development of neutrophilic airway inflammation." (PMID 36428547, 2022). "In addition to the classic TLRs/MyD88/NF-κB pathway, STING/IRF3/NLRP3 signaling is involved in the LPS-induced cardiac inflammation, apoptosis, and dysfunction." (PMID 35721566, 2022). "In agreement with our findings, a previous study found that miR-30b-5p was participated in cannabinoid receptor 1-mediated activation of NLRP3 inflammasome in macrophages, and miR-30b-5p agomir decreased the expression of NLRP3, thereby attenuating liver inflammation." (PMID 35500231, 2022). "However, when comparing NLRP3-KO-MCAO and WT-MCAO mice, lung injury was relieved, and mild lung inflammation occurred in the NLRP3-KO group, while severe lung inflammation was present in WT-MCAO mice." (PMID 35432726, 2022). "Abnormal activation of NLRP3 inflammasomes can lead to cardiac inflammation and heart dysfunction." (PMID 33270361, 2021). "Moreover, the LPS–TLR4 axis mediates NLRP3 inflammasome activation and induces the secretion of IL-1β/IL-18, which promotes cardiac inflammation." (PMID 34201938, 2021). "GSDMD participated in cardiac inflammation, and resulted in LPS-induced myocardial injury and cell death, by enriching in mitochondria, leading to mitochondrial dysfunction and overproduction of ROS, further regulating the activation of the NLRP3 inflammasome." (PMID 34820388, 2021). "Empagliflozin attenuated activation of the NLRP3 inflammasome and cardiac inflammation." (PMID 34776995, 2021). "However, the detailed signaling pathway for the synthesis of the NLRP3 inflammasome and IL-1β in neutrophil-dominant asthmatic airway inflammation remains to be determined." (PMID 34064821, 2021). "Moreover, SUD-MC actuated NLRP3 inflammasome-dependent pulmonary inflammation, as confirmed by the assays with NLRP3 inflammasome inhibitor and the NLRP3−/− mouse model." (PMID 32365944, 2020). "Moreover, in a recent paper, we observed that the in vivo direct irreversible inhibition of NLRP3 with INF39, a novel acrylate compound able to inhibit NLRP3 ATPase activity, exerts beneficial effects on bowel inflammation." (PMID 30559669, 2018). "In correlation with this observation, our data showed that 25-HC could act as a potent mediator and inducer of cerebral inflammation in CCALD through its ability to activate the NLRP3 inflammasome." (PMID 27779191, 2016). "Variations in genes encoding the NLRP3 inflammasome are associated with auto-inflammatory diseases, and Q705K in NLRP3 and C10X in CARD8 are two polymorphisms that, per se or combined, have been associated with increased risk and severity of chronic inflammation." (PMID 25400921, 2014). "We hypothesise that blockade of the P2X7 – NLRP3 inflammasome pathway will attenuate the inflammation present in CS-induced airway inflammation." (PMID 21915284, 2011).
inflammation (continued). "The NLRP3 inflammasome-mediated activation of caspase-1 contributes to a large spectrum of inflammatory diseases but so far little is known about its role in renal inflammation." (PMID 22046355, 2011). "Thus, the anti‐inflammatory and anti‐oxidant effects of linarin may play a major role in the protective effects of DO in airway inflammation of the LPS‐induced ALI model by inhibiting the TXNIP/NLRP3 inflammasome and activating the Nrf‐2 pathways." (PMID 40265676, 2025). "The NLRP3 inflammasome plays a role in various inflammatory diseases, and active components of TCMs, such as rhubarb-free anthraquinone, echinatin, gentiopicroside, Ginger essential oil, Paeonol, and Panaxydol, inhibit the activation of the NLRP3 inflammasome to improve liver inflammation in NAFLD." (PMID 41354800, 2025). "In addition, NLRP3-mediated AEC pyroptosis was found to be upregulated in obese asthmatic mice, when compared to control asthmatic mice, contributing to the exacerbation of lung inflammation associated with obesity." (PMID 39611173, 2024). "Consequently, food components targeting NLRP3 inflammasome activation may be a novel safe and effective strategy to prevent the initiation and progression of inflammation‐related diseases." (PMID 39425563, 2024). "In addition, it is still unknown whether inhibiting NLRP3, a key molecule involved in brain inflammation, reduces the degree of lung injury after the improvement of brain injury." (PMID 35432726, 2022). "Therefore, inhibiting NF-κB/NLRP3 signaling can help diminish TMAO-induced cardiac inflammation." (PMID 34201938, 2021). "In CIA mice, inhibition of NLRP3 or blockade of GSDMD pore formation mitigated joint swelling, reduced bone erosion, and attenuated synovial inflammation." (PMID 41089701, 2025). "A recent study has shown that LPS can activate the NLRP3/ASC/Caspase-1 signaling pathway, leading to renal inflammation and interstitial fibrosis." (PMID 39193336, 2024). "Additionally, (i) marathon runners experience NLRP3 inflammasome-related vascular inflammation, in which UCP1 expression may play a role, and (ii) a strong correlation between the upregulation of acute phase proteins and performing world-class/Olympic sports has been found." (PMID 36835062, 2023). "In conclusion, we have discovered a selective and potent small molecule inhibitor of the NLRP3 inflammasome and demonstrated its efficacy in murine models of CAPS and neutrophilic airway inflammation." (PMID 37598239, 2023). "In summary, findings uncovered in the current study highlighted the protective role of miR-135a-5p in NLRP3-mediated cardiac inflammation and fibrosis through the mechanism wherein miR-135a-5p inhibited TXNIP to reduce the binding of TXNIP and NLRP3." (PMID 35148667, 2022). "Recently, it is shown that GSDMD-dependent pyroptosis is triggered in silica-treated AMs by activating the TLR4/NLRP3/caspase-1/GSDMD pathway, which results in aggravated pulmonary inflammation and diffuses silicon nodules." (PMID 35819638, 2022). "Focusing on role of inflammasome, especially in brain inflammation, NF-κB/TLR4/NLRP3 inflammasome initiate signaling pathway." (PMID 36015160, 2022). "Studies have shown that NLRP3 knockout in nonalcoholic steatohepatitis (NASH) mice model inhibited the activation of NLRP3, ASC, and caspase-1 in liver and can significantly reduce liver inflammation in mice and prevent the development of the NASH disease." (PMID 33643422, 2021). "SZF suppresses the activation of the NLRP3-ASC-caspase-1 axis by inhibiting TXNIP, thus ameliorating renal inflammation." (PMID 29358971, 2017). "In this study, macrophage-derived NLRP3 inflammasome was identified as a platform essential for a systemic response to TsV, resulting in PGE2, IL-1β and LTB4 production, lung inflammation and mortality." (PMID 26907476, 2016).
inflammation (continued). "Alcohol‐induced hepatic inflammation involves a variety of complex mechanisms, the core mechanism of which lies in LPS translocation and its triggered hyperactivation of the TLR4/NF‐κB/NLRP3 inflammatory axis." (PMID 41509195, 2026). "Furthermore, by targeting NF-κB/NLRP3/IL-1β signaling, TRL mitigated bleomycin-induced pulmonary inflammation and fibrosis." (PMID 40698661, 2025). "In perfluorooctane sulfonate-induced asthmatic mice, macrophage pyroptosis was mediated by the AIM2 inflammasome, rather than the NLRP3 that exacerbates asthmatic lung inflammation through IL-1β." (PMID 39611173, 2024). "Other research demonstrates that ibrutinib reduces the activation of NF-κB and NLRP3 inflammasomes by targeting BTK and finally ameliorates pulmonary inflammation, suggesting that BTK might be a potential drug target for anti-inflammation." (PMID 37630287, 2023). "Intracellular miR-223/142 was delivered via microvesicle-mediated delivery, and miR-223 and miR-142 synergistically inhibited activation of the NLRP3 inflammasome in macrophages by inhibiting NLRP3 and ASC, respectively, leading to suppression of lung inflammation." (PMID 37378068, 2023). "In conclusion, the study identified a potential P2X7R antagonist, Z1456467176, that can inhibit ATP-induced NLRP3-caspase-1-IL-1β pathway activation by allosterically modulating P2X7R, effectively alleviating MSU crystal-induced gouty joint inflammation in rats." (PMID 36052144, 2022). "Thus, our studies suggest that the ‘5-/12-LOX-BLT1/2-NLRP3-IL-1β’ signaling cascade potentially contributes to NLRP3 inflammasome stimulation and IL-1β synthesis in HDM/LPS-driven neutrophilic airway inflammation." (PMID 34064821, 2021). "As a specific inhibitor of NLRP3, the protective effect of MCC950 on pulmonary inflammation, kidney fibrosis and other diseases has been well described, but its role in OIR mice is unknown." (PMID 33093455, 2020). "At present, however, no information is available on the role of NLRP3 inflammasomes in ouabain-induced cardiac inflammation." (PMID 28493895, 2017). "Our data suggest that 25-HC, but not VLCFA, contributes to the cerebral inflammation of X-ALD via activation of the NLRP3 inflammasome pathway." (PMID 27779191, 2016). "We conclude that there is a ceRNA relationship between GAS5, miR-223-3p, and NLRP3; PAMK alleviates LPS-induced pyroptosis in macrophages through the lncRNA GAS5/miR-223-3p/NLRP3 axis; and PAMK intervention in the macrophage pyroptosis process subsequently alleviates liver inflammation." (PMID 40799819, 2025). "Interestingly, as an effector of the NLRP3 inflammasome, IL‐1β is a pluripotent pro‐inflammatory cytokine involved in the process of PM2.5‐induced respiratory diseases and considered to play a pivotal role in pulmonary inflammation pathogenesis." (PMID 32996690, 2021). "However, the relationship between BLT1/2 and NLRP3 in neutrophil-dominant asthmatic airway inflammation has not been previously studied." (PMID 34064821, 2021). "Therefore, inhibition of NLRP3 inflammasome and GSDMD could be a potential therapeutic approach for the prevention and therapy of liver inflammation and fibrosis through regulating pyroptosis." (PMID 32071306, 2020).
metabolic disorders (214 papers, 2013 to 2026). "Beyond its involvement in immune responses, NLRP3 inflammasomes are intricately linked to the initiation and progression of various diseases, including metabolic disorders like type 2 diabetes, atherosclerosis, and neurodegenerative conditions." (PMID 38399989, 2024). "The excessive or aberrant activation of NLRP3 is strongly associated with the onset of various inflammatory diseases, autoimmune conditions, and metabolic disorders." (PMID 38399989, 2024). "Different studies have reported the association of NLRP3 polymorphisms with autoimmune, inflammatory, cardiovascular and metabolic diseases, but few reports have focused on the association of NLRP3 pathway-related gene variants with kidney diseases." (PMID 36835594, 2023). "Not only would NLRP3 activate and initiate the inflammatory response, but also directly damage tissue cells, causing metabolic disorders and lipid deposition, etc., which in turn further activates NLRP3." (PMID 36879310, 2023). "With the serious imbalance of metabolic disorder, increase of ROS and damage of mitochondria caused by chronic inflammation, the activation of NLRP3 inflammasome is activated." (PMID 36993972, 2023). "One key aspect is the role of chronic low-grade inflammation associated with metabolic disorders, which contributes to NLRP3 inflammasome activation and subsequent neuroinflammatory responses." (PMID 38068904, 2023). "Aberrant activation of the NLRP3 inflammasome can facilitate a chronic systemic low-grade inflammatory state that modulates inflammation-associated metabolic disorders." (PMID 38067561, 2023). "Dysregulation of NLRP3 inflammasome activation is linked with the development of many diseases, especially age-associated ailments such as neurologic disorders and metabolic diseases." (PMID 35514993, 2022). "The aberrant activation of the NLRP3 inflammasome is associated with the pathogenesis of various inflammatory, autoimmune and metabolic diseases, including atherosclerosis and T2D." (PMID 33806797, 2021). "The association of an inappropriately activated NLRP3 inflammasome with various auto-immune and inflammatory diseases, and neurodegenerative and metabolic disorders are well studied." (PMID 34684819, 2021). "So, inhibition of NLRP3 inflammasome-mediated production of IL-1β can improve the metabolic disorder associated with adipose tissue inflammation." (PMID 33796528, 2021). "Recent studies revealed an association between NLRP3 inflammasomes and metabolic disease-related lipid species, such as saturated fatty acids (SFAs) and ceramides." (PMID 33546399, 2021). "NLRP3 inflammasome is associated with onset and progression of various diseases, including metabolic disorders." (PMID 29802339, 2018). "Taken together, our results demonstrate that TR can reverse T2D‐associated metabolic disorders by inhibition of NLRP3 inflammasome." (PMID 29531021, 2018). "NLRP3 inflammasome has also been implicated in the pathogenesis of metabolic disorders such as type 2 diabetes, obesity, atherosclerosis, and gout." (PMID 29163487, 2017). "In recent years, the important role of NLRP3 inflammasome implicated in the development of metabolic diseases including T2D received increasing attention." (PMID 28786950, 2017). "Among the many inflammatory mediators, the cytoplasmic innate Nod-like receptor NLRP3 has been implicated in promoting metabolic disorders." (PMID 28588189, 2017). "Diverse reports have suggested that metabolic diseases are associated with chronic inflammation, in which NLRP3 inflammasome activation and IL-1β and IL-18 cytokine production have been implicated." (PMID 29151018, 2017). "NLRP3, as component of the inflammasome, is an important sensor of altered homeostasis and its deregulation is linked to a number of metabolic diseases." (PMID 29170442, 2017).